TRAV2 (T cell receptor alpha variable 2)
Description:
V region of the variable domain of T cell receptor (TR) alpha chain that participates in the antigen recognition. Alpha-beta T cell receptors are antigen specific receptors which are essential to the immune response and are present on the cell surface of T lymphocytes. Recognize peptide-major histocompatibility (MH) (pMH) complexes that are displayed by antigen presenting cells (APC), a prerequisite for efficient T cell adaptive immunity against pathogens. Binding of alpha-beta TR to pMH complex initiates TR-CD3 clustering on the cell surface and intracellular activation of LCK that phosphorylates the ITAM motifs of CD3G, CD3D, CD3E and CD247 enabling the recruitment of ZAP70. In turn ZAP70 phosphorylates LAT, which recruits numerous signaling molecules to form the LAT signalosome. The LAT signalosome propagates signal branching to three major signaling pathways, the calcium, the mitogen-activated protein kinase (MAPK) kinase and the nuclear factor NF-kappa-B (NF-kB) pathways, leading to the mobilization of transcription factors that are critical for gene expression and essential for T cell growth and differentiation. The T cell repertoire is generated in the thymus, by V-(D)-J rearrangement. This repertoire is then shaped by intrathymic selection events to generate a peripheral T cell pool of self-MH restricted, non-autoaggressive T cells. Post-thymic interaction of alpha-beta TR with the pMH complexes shapes TR structural and functional avidity.
Synonyms: TCRAV11S1; TCRAV2S1
Gene: T-cell receptor variable (V) gene on chromosome 14 (21,712,321 to 21,712,843, forward strand). Ensembl gene ENSG00000211776.
Subcellular location: Cell membrane
Gene Ontology:
Biological process: immune response
Cellular component: immunoglobulin complex; plasma membrane
Homologues: Orthologues: macaque TRAV2 (71% identical), pig TRAV2 (64% identical).
Diseases named in the same sentence as TRAV2 in open-access papers:
TRAV2 is named in the same sentence as 1 disease in open-access papers, as found by Europe PMC text mining. Sharing a sentence is not in itself a finding about the gene and the disease.
TRAV2 shares sentences with these, for which no sentence is quoted: tumor (1 paper).